VLDLR (very low density lipoprotein receptor)
Diseases named in the same sentence as VLDLR in open-access papers (continued):
Sharing a sentence is not in itself a finding about the gene and the disease.
tumor (15 papers, 2015 to 2024). "To further determine the effects of VLDLR on tumor growth in vivo, we subcutaneously inoculated nude mice with MDA-MB-231 stable cells expressing inducible shNC or shVLDLRs into dorsal flank." (PMID 36568166, 2022). "Tumor volume was monitored from day 0 to day 20 after inoculation, and the results showed that the tumors derived from VLDLR silenced cells grew significantly slower than tumors derived from control cells." (PMID 36568166, 2022). "Collectively, these results demonstrated that VLDLR silencing inhibited the tumor development in vivo." (PMID 36568166, 2022). "Though the critical role of VLDLR in tumor development has been reported in various cancer types, the function of VLDLR has not been investigated in BCSCs." (PMID 36568166, 2022). "Peritumorally, VLDLR stained weakly positive in 66% of the cases (8/ 12), while in 16% of the cases (5/ 32) VLDLR was weakly positive both within the tumor and peritumorally." (PMID 28255385, 2017). "EV-mediated transfer of linc-VLDLR is involved in HCC tumor cell response to chemotherapy by modulating cell-cell communication in the tumor microenvironment." (PMID 27713136, 2017). "Recently, the very-low-density lipoprotein receptor (VLDLR), apolipoprotein E receptor 2 (ApoER2), and the CD147 protein complex, which are associated with tumor proliferation and the inhibition of apoptosis, have also been revealed to be associated with the entry of the SINV into cells." (PMID 39000311, 2024). "A possible explanation for these divergent results is the high degree of molecular heterogeneity of malignant tumor cells which might also include the expression of functional VLDLr." (PMID 33998175, 2021). "Lnc-VLDLR expressed in EV promotes tumor cell death and releases noe-antigen." (PMID 33194608, 2020). "VLDLR is a member of the low-density lipoprotein receptor superfamily which is involved in receptor-mediated endocytosis of specific ligands and has been reported to play a role in pathogenesis and tumor cell proliferation." (PMID 27957497, 2016). "Ferroptosis analysis indicated that ALOX5 and VLDLR were the top CAPG-related ferroptosis markers; glutathione metabolism levels in tumor group were generally high, and decitabine was a ferroptosis inducer." (PMID 39600941, 2024). "Results showed that the relative expression of LEF1, VLDLR, RARRES2 and TNFRSF10C were significantly up-regulated compared to adjacent non-tumor tissues and other metastatic sites (P < 0.05)." (PMID 34256750, 2021). "Lnc-VLDLR (very low-density lipoprotein-receptor-VLDLR) is expressed in extracellular vesicles (EV) and promotes tumor cell death during chemotherapy, leading to increased chemotherapy efficiency." (PMID 33194608, 2020). "First, the mRNA levels of VLDLR were examined with tumor tissues, which comprised cancer cells and non-cancer cells within the tumor microenvironment, possibly making the evaluation of VLDLR mRNA inaccurate." (PMID 36568166, 2022).
cancer (14 papers, 2010 to 2026). A tumor composed of atypical neoplastic, often pleomorphic cells that invade other tissues. "Enhanced expression of very low density lipoprotein receptor (VLDLR) in the intestine has been associated with stimulated cell proliferation and cancer development, hence with an increased energy demand." (PMID 34202278, 2021). "Abnormal VLDLR expression has been associated with the pathogenesis of various cancers." (PMID 36568166, 2022). "The decreased expression of very low-density-lipoprotein receptor (VLDLR) in cancer cell membranes contributes to the accumulation of cholesterol in the cytoplasm." (PMID 38238756, 2024). "CDKN2A displayed higher mutation rates across multiple cancer types (31%), and other frequently mutated genes included LRPPRC (13%), PRKAA2 (11%), VLDLR (9%), ASNS (8%), GZMA (7%), GLS (7%), TNFRSF1A (6%), PSAT1 (5%), and PRDX6 (4%)." (PMID 37534256, 2023). "Some studies revealed that VLDLR promotes the growth of cancer cells by binding to the uPA/PAI-1 complex, or by regulating the stability of β-catenin." (PMID 36568166, 2022). "Moreover, VLDLR-II overexpression promoted, while VLDLR-I transfection reduced, cancer cell proliferation and migration in a gastric adenocarcinoma cell line, indicating the controversial effects of two VLDLR subtypes." (PMID 36568166, 2022). "Collectively, lipid-independent function of VLDLR was involved in cancer cell proliferation." (PMID 36568166, 2022). "Even though VLDLR promoted cell growth at a lower level under lipid-depleted conditions, our results suggested that the lipid-independent function of VLDLR was involved in cancer cell proliferation." (PMID 36568166, 2022). "The six main genes are involved in the cancer and inflammatory processes (YWHAZ, CCL2 and SMPD2) and lipid droplet formation and metabolism (CIDEC, VLDLR and FASN) and significantly increased in NASH patients compared to control or NAFL groups." (PMID 31717414, 2019). "Given that the numbers of spheres were reduced by more than 50% upon VLDLR knockdown, we proposed that the increased cell apoptosis was not enough to explain the inhibited cancer stem cell function in VLDLR silenced cells." (PMID 36568166, 2022). "However, we presented that cancer cell proliferation was highly dependent on VLDLR expression, suggesting that cancer recurrence is difficult to occur without VLDLR expression." (PMID 36568166, 2022). "We treated cancer cells with GST-RAP fusion protein and found that cell proliferation promoted by VLDLR-I and VLDLR-II overexpression was not affected, suggesting that the ligand binding activity was not involved in the cancer-promoting function of VLDLR." (PMID 36568166, 2022).
neurodevelopmental disorder (3 papers, 2017 to 2024). A behavioral and cognitive disorder with onset during the developmental period that involves impaired or aberrant development of intellectual, motor, or social functions. "As the majority of previously reported VLDLR pathogenic variants are loss-of-function variants, homozygosity of the novel VLDLR stop-gain variant likely underlies the neurodevelopmental disorder in the two sisters." (PMID 39085459, 2024).
adenocarcinoma (1 paper, 2010). A common cancer characterized by the presence of malignant glandular cells. "Our group previously reported that enhanced activity of type II VLDLR (VLDLR II), one subtype of VLDLR, promotes adenocarcinoma SGC7901 cells proliferation and migration." (PMID 21047397, 2010).
infectious disease (1 paper, 2019). A disorder directly resulting from the presence and activity of a microbial, viral, or parasitic agent in humans. "Additionally, some of these target genes, including SOD2, TNFAIP3, ARG1, SERPINB2, VLDLR, HSPA5, and LCN2, are associated with infectious diseases, suggesting that lncRNAs respond to PCV2 infection by regulating these genes." (PMID 30863688, 2019).
VLDLR also shares sentences with these, for which no sentence is quoted: Ataxia (5 papers); autism (3); Hypertriglyceridaemia (3); nervous system disorder (3); Dandy-Walker malformation (2); dementia (2); gastric cancer (2); glioblastoma (2); Intellectual disability (2); lipid metabolism disorder (2); microcephaly (2); muscle-eye-brain disease (2); neurodegenerative disease (2); acute myeloid leukemia (1); Allergy (1); Aortic dissection (1); Atherosclerotic lesion (1); cardiovascular disease (1); cervix cancer (1); cognitive disorder (1); colorectal cancer (1); congenital disorder of glycosylation (1); congenital disorder of glycosylation type Ia (1); congenital muscular dystrophies (1); coronary artery disease (1); gallbladder cancer (1); genetic diseases (1); glioma (1); hay fever (1); Hyperglycemia (1).
A further 23 diseases each share a sentence with VLDLR in 1 paper.